GUCA1A (guanylate cyclase activator 1A)
Description:
Stimulates retinal guanylyl cyclase when free calcium ions concentration is low and inhibits guanylyl cyclase when free calcium ions concentration is elevated. This Ca(2+)-sensitive regulation of retinal guanylyl cyclase is a key event in recovery of the dark state of rod photoreceptors following light exposure (By similarity). May be involved in cone photoreceptor light response and recovery of response in bright light (By similarity).
Synonyms: C6orf131; GCAP; GCAP1; GUCA1; COD3; dJ139D8.6; CORD14; GCAP-I; GCAP-1; GUCA
Tractability: No criterion of Open Targets' tractability assessment is met for any kind of drug.
Gene: Protein-coding gene on chromosome 6 (42,173,364 to 42,181,338, forward strand). Ensembl gene ENSG00000048545.
Subcellular location: Membrane; Photoreceptor inner segment; Cell projection, cilium, photoreceptor outer segment
Subcellular location (Human Protein Atlas): Plasma membrane
Pathways (Reactome):
Sensory Perception: Inactivation, recovery and regulation of the phototransduction cascade
Gene Ontology:
Molecular function: guanylate cyclase regulator activity; protein binding; calcium ion binding; calcium sensitive guanylate cyclase activator activity
Biological process: visual perception; cellular response to calcium ion; positive regulation of guanylate cyclase activity; regulation of signal transduction; signal transduction
Cellular component: cone photoreceptor outer segment; photoreceptor inner segment; photoreceptor outer segment membrane; photoreceptor disc membrane; membrane; photoreceptor outer segment
Genetic constraint (gnomAD): Loss-of-function variants: 14 observed, 20.43 expected, observed/expected ratio (o/e) 0.69, 90% interval 0.45 to 1.07. The upper end of that interval is the gene's LOEUF score, 1.07, which puts it in group 4 of 6, group 1 being the genes least tolerant of losing a copy. Missense variants: 264 observed, 274.51 expected, observed/expected ratio (o/e) 0.96, 90% interval 0.87 to 1.07. Synonymous variants: 97 observed, 107.41 expected, observed/expected ratio (o/e) 0.9, 90% interval 0.76 to 1.07.
Gene-disease validity (ClinGen):
ClinGen rates the evidence that GUCA1A causes each of these diseases.
cone dystrophy 3 (autosomal dominant): Definitive. Any cone dystrophy in which the cause of the disease is a mutation in the GUCA1A gene.
Homologues: Orthologues: macaque GUCA1A (99% identical), chimpanzee GUCA1A (98% identical), dog GUCA1A (96% identical), pig GUCA1A (96% identical), rat Guca1a (93% identical), mouse Guca1a (92% identical), guinea pig GUCA1A (91% identical), rabbit GUCA1A (79% identical), tropical clawed frog guca1a (74% identical), zebrafish guca1ab.2 (62% identical), zebrafish guca1ab.1 (61% identical), Caenorhabditis elegans ncs-2 (32% identical), and 3 more. Paralogues in human: GUCA1C (45% identical), GUCA1B (43% identical), HPCAL1 (38% identical), VSNL1 (37% identical), HPCA (37% identical), NCALD (37% identical), HPCAL4 (36% identical), NCS1 (34% identical), RCVRN (31% identical), KCNIP1 (30% identical), KCNIP2 (29% identical), KCNIP3 (26% identical), and 2 more.
Diseases named in the same sentence as GUCA1A in open-access papers:
GUCA1A is named in the same sentence as 20 diseases in open-access papers, as found by Europe PMC text mining. Sharing a sentence is not in itself a finding about the gene and the disease. The quoted sentences say what the papers report.
cone-rod dystrophy (20 papers, 2011 to 2025). Inherited retinal dystrophies that belong to the group of pigmentary retinopathies. "Previous studies showed that cone-rod dystrophy and macular dystrophy were associated with the GUCA1A gene mutation." (PMID 39286023, 2024). "The guanylate cyclase activator 1A gene (GUCA1A), located in 6p21.1, encodes guanylyl cyclase-activating protein 1 (GCAP1), and has been identified as being involved in dominant cone dystrophy, cone-rod dystrophy and macular dystrophy." (PMID 35651940, 2022). "The mutation of GUCA1A, guanylyl cyclase-activating protein 1, would lead to a severe dominantly inherited retinal degeneration (Cone dystrophy 3)." (PMID 31032367, 2019). "It is known that mutations in GUCA1A cause autosomal dominant cone dystrophy or cone-rod dystrophy (CRD) [MIM: 602093]." (PMID 27788217, 2016). "Ten heterozygous mutations in the GUCA1A gene encoding GCAP1 have been linked to autosomal dominant cone dystrophy (adCD), cone rod dystrophy (adCRD) or macular degeneration (adMD)." (PMID 25058152, 2014). "Dominant mutations occurring in the high-affinity Ca2+-binding sites (EF-hands) of the GUCA1A gene encoding guanylate cyclase-activating protein 1 (GCAP1) cause slowly progressing cone-rod dystrophy (CORD) in a dozen families worldwide." (PMID 23472098, 2013). "Recently, a novel missense mutation (G86R) was found in GUCA1A, the gene encoding for GCAP1, in patients diagnosed with cone-rod dystrophy." (PMID 31979372, 2020). "GUCA1A gene variants are associated with autosomal dominant (AD) cone dystrophy (COD) and cone-rod dystrophy (CORD)." (PMID 31728034, 2019).
retinal degeneration (11 papers, 2011 to 2025). Degeneration of the retina. "Mutations in GUCA1A, encoding for GCAP1 result in aberrant GC regulation and in retinal degeneration, a set of progressive diseases involving cones, the macula, and in some cases rods, ultimately leading to blindness." (PMID 31979372, 2020). "Since promising strategies for the delivery of WT recombinant proteins to photoreceptors are under development, our findings might be relevant for future protein therapies aimed at slowing retinal degenerations associated with GUCA1A mutants." (PMID 31882816, 2019). "Cone dystrophy 3 (COD3) is a severe dominantly inherited retinal degeneration caused by missense mutations in GUCA1A, the gene encoding Guanylate Cyclase Activating Protein 1 (GCAP1)." (PMID 21464903, 2011). "Pathogenic or likely pathogenic variants were identified predominantly in genes already known to cause retinal degenerations (with a significant number of ABCA4 variants), although variants in genes newly identified as involved in retinal disorders were also uncovered (such as CFAP410 and GUCA1A)." (PMID 39202371, 2024).
cone dystrophy (10 papers, 2007 to 2025). An inherited ocular disorder characterized by the loss of cone cells, the photoreceptors responsible for both central and color vision. "GUCA1A p.D100E, another mutation previously implicated in cone dystrophy, also impaired the retinal pigment epithelium and photoreceptors in zebrafish, but probably via a dominant negative effect." (PMID 28125083, 2017). "Belonging to this 2nd category, mutations of GUCA1A have been described in one family with autosomal dominant CRD, while all other GUCA1A mutations are responsible for cone dystrophies." (PMID 17270046, 2007). "The mutation of GUCA1A has been identified to be associated with cone dystrophies and maculopathy." (PMID 35742911, 2022). "The retinal disease seen in human patients with dominant mutations in GUCA1A was originally described as an isolated cone dystrophy, but recent evidence suggests that secondary loss of rod function may occur in some patients, particularly at later stages of disease." (PMID 21464903, 2011). "GUCA1A p.D100E was previously reported to be correlated with cone dystrophy; therefore, we next tried to determine whether the pathogenesis of p.D100E differed from that of p.R120L." (PMID 28125083, 2017).
retinal dystrophies (9 papers, 2013 to 2023). "Mutations in both proteins have been shown to cause retinal dystrophies, albeit with more severe phenotypes seen for guca1a (GCAP1) mutations." (PMID 37008786, 2023). "The relative preservation of rod responses in most GUCA1A-associated progressive retinal dystrophies is attributed to greater GCAP1 expression in cones." (PMID 30679166, 2019). "To date, 20 missense mutations have been found in the GUCA1A gene encoding GCAP1, which have been associated with cone (COD) or cone-rod (CORD) dystrophies, severe forms of retinal dystrophy characterized by central vision loss, impaired color vision and photophobia." (PMID 31882816, 2019).
Macular dystrophy (4 papers, 2013 to 2025). Macular dystrophy is a nonspecific term for retinal degeneration, generally confined to the macula, usually presumed of genetic origin.
Photophobia (3 papers, 2021 to 2023). Excessive sensitivity to light with the sensation of discomfort or pain in the eyes due to exposure to bright light. "The gene coding for GCAP1, named GUCA1A, has been associated with autosomal dominant cone dystrophies (adCOD), a class of severe retinal degeneration diseases characterized by central vision loss, impaired color vision, and photophobia." (PMID 34639157, 2021).
central areolar choroidal dystrophy (1 paper, 2017). "In this study we found a novel GUCA1A mutation to be disease causative in a five-generation family affected with variable maculopathies ranging from mild photoreceptor degeneration to central areolar choroidal dystrophy (CACD)." (PMID 28125083, 2017). "We conclude that GUCA1A mutations could cause significant variability in maculopathies, including central areolar choroidal dystrophy, which represents a severe pattern of maculopathy." (PMID 28125083, 2017).
Retinal atrophy (1 paper, 2019). A nonspecific term denoting wasting, especially as a result of degeneration, of the retinal pigment epithelium (RPE) and neurosensory retinal cells. "Associations with GUCA1A mutations have also been reported, but in our cohort, the only patient with a mutation on this gene revealed an extensive retinal atrophy." (PMID 31574917, 2019).
tumor (2 papers, 2020 to 2024). "Elevated expression of LOXL1, LOXL4 and GUCA1A was detected in tumour cells." (PMID 39286023, 2024). "Regardless, we still observed abnormal methylation patterns, that might suggest role in the expression of some genes characterizing tumor classes (e.g. expression of LRN4 and GUCA1A negatively correlated with promoter CpG islands average methylation)." (PMID 32433524, 2020).
GUCA1A also shares sentences with these, for which no sentence is quoted: retinal disease (7 papers); retinitis pigmentosa (5); Blindness (4); retinopathies (3); autosomal dominant retinitis pigmentosa (2); dominant cone/cone-rod dystrophy (2); cone dystrophy 3 (1); macular degeneration (1); osteoarthritis (1); retinitis (1); retinoblastoma (1).